GSK3B (glycogen synthase kinase 3 beta)
Diseases named in the same sentence as GSK3B in open-access papers (continued):
Sharing a sentence is not in itself a finding about the gene and the disease.
cancer (continued). "Furthermore, lithium, which is known for its GSK-3β inhibitory activity, has been shown to enhance the anti-cancer activity of gemcitabine via downregulation of the hedgehog-GLI1 pathway." (PMID 34356465, 2021). "Upon phosphorylation by GSK3β, β-catenin is degraded via the ubiquitin-proteasome system; GSK3β is therefore recognized as a key player in the regulation of β-catenin function, particularly in the promotion of cancer growth." (PMID 34198826, 2021). "On the other hand, GSK3β is overexpressed in certain cancers such as colon, liver, and pancreas." (PMID 34367990, 2021). "However, contemporary research has focused mostly on GSK-3β in the context of cancer, especially in PDAC." (PMID 34356465, 2021). "Ellagic acid was also predicted to inhibit the tumor suppressor GSK3b, but interestingly, experiments show that inhibition of GSK3b may in fact decrease cancer cell proliferation." (PMID 36303742, 2021). "Besides, it has been widely documented that the genetic alterations in GSK-3β impinge on the tumorigenesis, tumor development, epithelial–mesenchymal transition, and cancer metastasis, as well as therapy resistance in multiple cancers." (PMID 34732689, 2021). "After 6 h, the total protein was extracted for phosphorylation protein microarray analysis, which found that AKT and GSK3β protein phosphorylation ratios in the sh-cancer-IgG group were reduced and that Bcl-2, BAD, caspase 3, caspase 9, and BAX apoptosis-related proteins increased." (PMID 34150640, 2021). "As a consequence, there is a growing interest in GSK3β as a therapeutic target in cancer." (PMID 34023818, 2021). "When cancer occurs, the Wnt pathway is activated, triggering the phosphorylation of Dvl, and then, the activity of GSK-3β is inhibited, thereby attenuating β-catenin phosphorylation and ultimately suppressing the degradation of β-catenin and thus promoting its nuclear translocation." (PMID 34330894, 2021). "In contrast, both HDAC1 and GSK3B are regularly dysregulated in cancer; thus it is probable that various Drosha PTMs may be observed in cancer cells in comparison with nontumor cells." (PMID 34721577, 2021). "Further, the differences in the function of GSK-3β in various cancer types may hinder the study of ABZ as a potentially broad-spectrum cancer metastasis inhibitor." (PMID 34966427, 2021). "The ILK/Akt/GSK3β axis has been reported to play roles in cancer cell growth and survival." (PMID 34591063, 2021). "Therefore, it seems that GSK3B participates in multiple molecular pathways used by various cancer types to evade chemotherapy, radiotherapy and targeted therapies." (PMID 34065438, 2021). "In addition, miRNAs are also involved in the cancer stem cell generation, epithelial to mesenchymal transition, invasion, and metastasis via regulating the signaling pathway of GSK-3β participation." (PMID 34485505, 2021). "Given this, it is highly likely that the different outcomes of GSK3β inhibition may be specific to different tissues and cancer types." (PMID 34367990, 2021). "GSK3β plays multiple roles in different cancers, but its importance is still controversial." (PMID 33557839, 2021). "Moreover, GSK-3β positively regulates NF-κB activation and affects NF-κB–mediated survival and proliferation of cancer cells." (PMID 34955846, 2021). "Moreover, GSK-3, especially GSK-3β, limits the activation of NK cells, key innate effectors in cancer immunosurveillance, triggered by diverse activating receptors." (PMID 33918810, 2021). "We have seen above that the sexual dimorphism occurring in GSK3β-dependent regulation of adult stem cells could be inversed during the transition from inflammation to cancer." (PMID 33498808, 2021). "Previous studies revealed that the role of GSK3β in cancer progression were context-dependent." (PMID 34403222, 2021). "Integrin and growth factor receptors can activate GSK3β, and the lack of integrin α9 in a cancer cell is associated with higher GSK3β activity." (PMID 34027892, 2021).
cancer (continued). "Taken together, these findings suggest further investigation of the role of GSK-3β in cancer cells." (PMID 34955846, 2021). "Furthermore, it was reported that activation of GSK-3β contributed to arsenic trioxide-induced apoptosis in cancer cells." (PMID 34880920, 2021). "Importantly, due to the different pools of GSK3β, an aggressive cancer stem cell can cumulate both active GSK3β-dependent survival and β-catenin-dependent self-renewal deregulation." (PMID 33498808, 2021). "Additionally, overexpression of miR-744 and miR-940, which are microRNAs capable of targeting and downregulating GSK-3β mRNA, was found to inhibit cancer cell invasion." (PMID 34356465, 2021). "It was previously documented that GSK-3β has different effects on cancer cells." (PMID 34069111, 2021). "In NK cells, active GSK-3β has been associated with functional impairment and in line treatment with GSK-3β inhibitors increased in vitro cytotoxicity mediated by NK cells derived from both healthy donors and patients with cancer." (PMID 33572396, 2021). "They identified KIF11 inhibitor (originally indicated for several types of cancers), GSK3B inhibitor (originally indicated for several types of cancers), and AP-1 inhibitor (originally indicated for RA) as potential candidates for a repurposed treatment of T2D." (PMID 33691789, 2021). "Finally, growing evidence marks GSK3β as a potential therapeutic target in cancer, thus encouraging the development of GSK3β inhibitors for cancer treatment." (PMID 34064046, 2021). "AKT, a Serine/Threonine kinase, is a key component in numerous processes, can phosphorylate and then regulate vital downstream effector molecules, including FOXO, mTOR, GSK3b, and promote cancer cell growth, metabolism and survival and induce EMT and metastasis." (PMID 33088219, 2020). "Moreover, certain GSK-3β inhibitors will increase the sensitivity of certain cancer cells to chemotherapy." (PMID 32365809, 2020). "We illustrated that direct manipulation of GSK-3β/β-catenin pathway could modulate cancer stemness (P < 0.05), and also excluded the effects of Wnt on activation of GSK-3β/β-catenin pathway during this process (P < 0.01)." (PMID 32024815, 2020). "Moreover, in colon RKO cancer cells expressing wild-type Wnt/β-catenin, AdoMet enhanced GSK3β-mediated degradation of β-catenin by elevating the activity of protein phosphatase 2A." (PMID 33374288, 2020). "However, in some cancer models, As-IV inhibits the Akt/GSK-3β/β-catenin signaling axis by decreasing the phosphorylated forms of Akt and GSK-3β26,27." (PMID 32818074, 2020). "Our results are in line with a diverse role of GSK-3β in cancer's context and may support a general dysregulation of Wnt and EMT in some cancers." (PMID 32681294, 2020). "Considering this background, we hypothesized that simultaneously inhibiting GSK3B and HDACs would prevent cancer cell growth while also inhibiting EMT and its effect on metastasis and chemoresistance." (PMID 32698955, 2020). "The effects of LY294002 were observed also in CK2β-downregulated cells, suggesting that reducing GSK3β pS9 could be a strategy to control Snail1 levels in any situation where CK2β is defective, as possibly occurring in cancer cells." (PMID 31910234, 2020). "A therapeutic effect from GSK3β inhibition has been demonstrated in 25 different cancer types." (PMID 32503133, 2020). "GSK3β could, therefore, be a potential target that would allow adequate control of cancer pain by opioids." (PMID 32503133, 2020). "Therefore, DAX1 promotes cancer cell growth and tumorigenicity by allowing β-catenin to escape degradation via GSK3β." (PMID 32758292, 2020). "In addition to proteasomal degradation, SA-49-induced PD-L1 autophagic degradation by the PKCα/GSK3β/MITF pathway results in enhanced T cell killing of cancer cells." (PMID 33159034, 2020).
cancer (continued). "Different expression and activation levels of GLI3-FL regulators (SPOP, androgen receptor, PP2A, CBP, SET7, MED12) or regulators of GLI3-R (PKA, GSK3β, βTrCP) in cancer cells in comparison to healthy cells might also promote cancer cell growth and survival." (PMID 32245491, 2020). "We have also found increased β-catenin, SOX2 and GSK-3β protein expression between Caki-1 DC and Caki-1WT, which could suggest cancer stem-cell-like (CSC) and epithelial-mesenchymal transition (EMT) characteristics in Caki-1 DC." (PMID 32041631, 2020). "It is thus widely attempted to design GSK-3β inhibitor for cancer treatment 36-38." (PMID 31938062, 2020). "Despite evidence of a substantial anti-survival role of GSK-3β in some cancers, GSK-3β may promote the growth and survival of cancer cells through several mechanisms." (PMID 32526891, 2020). "Furthermore inhibition of GSK3β Tyr216 phosphorylation decreased the survival and/or proliferation of different types of cancer, both in vitro and in vivo." (PMID 31220102, 2019). "Taken together, our data suggests that the combined treatment with both Chk1 and GSK3-β inhibitors could be a novel effective therapy in triple negative cancers, but also possibly in other cancers in which inhibition of GSK3-β enhances Chk1 activation." (PMID 31362447, 2019). "Therefore, the reposition of lithium as an inhibitor of GSK-3β has emerged as a potential tool in cancer treatment." (PMID 31750236, 2019). "In summary, our results demonstrated that miR-188-5p, by targeting PTEN, increases Akt and GSK3β phosphorylation, thus promoting β-catenin nuclear accumulation and activating Wnt/β-catenin signaling, which enhances cancer metastasis and leads to poor prognosis in patients with GC." (PMID 31138169, 2019). "Additionally, the study demonstrated that STAT3 was a target of GSK3β using cancer phospho-antibody array and that enhanced GSK3β expression promoted ESCC progression through STAT3 in vitro and in vivo." (PMID 31888532, 2019). "Deregulation of GSK3β has been involved in diabetes, schizophrenia, Alzheimer disease and cancer." (PMID 31220102, 2019). "Indeed, many phytochemicals with anti-cancer activity induced GSK3β-dependent cyclin D1 degradation." (PMID 30736789, 2019). "Additionally, targeting GSK-3β is considered a promising anti-cancer therapeutic strategy by inhibiting NF-κB-targeted gene expression." (PMID 31546731, 2019). "GSK-3β has been shown as a positive regulator of NF-κB-mediated chemoresistance of cancer cells." (PMID 31882719, 2019). "We then found that AKT/GSK-3β signaling is necessary for JSD to exhibit its anti-cancers effects." (PMID 31772677, 2019). "An alternative mTORC1 transcription route through 4E-BP134 could also be active, since RGC survive after ONC in 4E-BP knock-out mice, possibly through a direct link (recently demonstrated in a cancer cell line) between GSK3β and 4E-BP1." (PMID 31443508, 2019). "Previous studies also reported that dysregulation of Src and GSK3β signaling could mediate cancer progression, metastasis, drug resistance, and ultimately transform into cancer stem cell phenotypes." (PMID 29747452, 2018). "In addition, these compounds are inhibitors of several important kinases implicated in cancer and neurodegeneration—casein kinase 1d (CK1d), CDK5, and glycogen synthase kinase 3-β (GSK3-β)." (PMID 29757250, 2018). "In previous studies, indirubins had been evaluated against a variety of diseases particularly in cancer and neurodegenerative disease therapy studies and have been shown to be potent inhibitors of mammalian kinases such as CDKs, GSK-3β, DYRKs and Aurora kinases." (PMID 30387370, 2018). "Considering all of this background knowledge collectively, we hypothesize that GSK3β may sustain the mitotic process in cancer cells by interacting with critical mitotic mediators such as TPR and dynein sub-complexes." (PMID 29568361, 2018).
cancer (continued). "Furthermore, GSK3β has been reported to regulate the resistance to chemotherapy in a variety of cancer cells." (PMID 30275459, 2018). "The protein amount of LSD1 was decreased in GSK3β-knocked down cancer cells, but such decrease could be inhibited by treatment with MG132." (PMID 29593255, 2018). "Dysregulation of GSK3β has been observed in various human cancers." (PMID 29700285, 2018). "Notably, roles for GSK3β and microRNAs in epithelial–mesenchymal transition and cancer stem cells were reported recently." (PMID 29568361, 2018). "Moreover, we and other groups have demonstrated the preferential therapeutic effect of GSK3β inhibition against these cancers, underscoring this kinase as a promising target in cancer treatment." (PMID 29568361, 2018). "Indeed, mutant KRas-dependent human cancer cells undergo apoptosis only when both GSK3α and GSK3β are knocked down simultaneously." (PMID 30514931, 2018). "Recently, a paper has revealed that CTT induced apoptosis in NSCLC through PTEN-mediated inhibition of the PI3K/Akt pathway; however, no studies have been investigated on the anti-cancer effects of CTT through the PI3K/Akt/ GSK-3β pathway and the comparison with existing anti-cancer drugs." (PMID 30217003, 2018). "Consequently, our study indicate that induction of mitotic catastrophe underpins the cancer therapeutic effect of GSK3β inhibition." (PMID 29568361, 2018). "The role of GSK-3β in cancer, particularly NSCLC and radiosensitivity, is unclear." (PMID 29793508, 2018). "GSK3β plays an important but paradoxical role in cancer processes." (PMID 30275459, 2018). "In cancer, GSK3β has been shown to be involved in the generation of cancer stem cells." (PMID 28766886, 2017). "Whereas Shimura's study indicated that IR could activate AKT/GSK3β/cyclin D1 pathway resulting in cancer cell enhanced proliferation and radioresistance." (PMID 28061440, 2017). "Aberrant trafficking of nascent clathrin-coated vesicles and alteration of cell signalling and enhancement of cell proliferation; dynamin 1 is acutely activated by an Akt/GSK3β signalling cascade to increase the rate of CCP initiation in the H1299 cancer cells." (PMID 28402939, 2017). "Using a cell-based GR activity assay that measures Dexamethasone (Dex)-mediated NF-κB repression, we have screened ~8,000 compounds and identified several compounds that suppressed GR activity, including multiple GSK3β inhibitors and anti-cancer agent camptothecin." (PMID 28785063, 2017). "This could also strengthen the deactivation of Gsk3-β and therefore contribute as potential targets of pathway crosstalk within cancer cells." (PMID 28926938, 2017). "Interestingly, glycogen synthase kinase 3β (GSK3β) activity has recently been shown to participate in gliomagenesis via maintenance of the stem population of cancer cells." (PMID 29053791, 2017). "The role of GSK3β in cancer has been discussed and remains controversial." (PMID 28800359, 2017). "In addition to affective disorders and neurodegeneration, GSK3B in mitochondria is deeply involved in the anti-apoptotic phenotype that characterizes cancer cells." (PMID 29127487, 2017). "GSK-3β plays an important role in regulating tRXRα production by calpain II in cancer cells." (PMID 29137318, 2017). "The inactivation of GSK3β has been identified as an important event in cancer progression." (PMID 27752740, 2017). "This role of GSK-3β is at direct odds with its established identity as a pro-apoptotic molecule and thus could be a potential drug target in cancer metastasis." (PMID 28821798, 2017). "Furthermore, PPAR-γ agonists downregulate key pathways of the insulin/IGF axis, such as PI3K/mTOR, MAPK, and GSK3β/Wnt/β-catenin cascades, which regulate cancer cell growth, proliferation, cell reprogramming, and differentiation." (PMID 28275367, 2017).
cancer (continued). "Also, our further study on HeLa cancer cells showed consistent results that PIWIL2 suppresses the interaction between GSK3β and BMAL1, leading to the failure of ubiquitination and degradation of the latter protein." (PMID 28903391, 2017). "To explore the molecular mechanisms through which miR-23b and ST7L regulated tumorigenesis and metastasis of HCC, we examined effector molecules of AKT/GSK3β/β-catenin signaling pathway, which was related with tumorigenesis and metastasis of many cancers including HCC." (PMID 28518144, 2017). "AKT/GSK-3β/β-catenin signaling participates in the stemness maintenance of cancer cells in HCC35." (PMID 28526827, 2017). "Our results suggested that C. militaris might be able to inhibit cancer growth through regulation of p85/AKT-dependent or GSK3β-related caspase-3-dependent apoptosis." (PMID 28761499, 2017). "Furthermore, glycogen synthase kinase-3 β (GSK3β) and nuclear factor (NF)-κB are key proteins controlling cancer metastasis." (PMID 28076326, 2017). "Furthermore, GSK3β has been extensively investigated for its role in cancer progression where it is reported to be under control of several different pathway including PI3K/Akt/mTOR, Ras/Raf/MEK/ERK, Wnt/β-catenin, Hedgehog, and Notch80." (PMID 28484273, 2017). "There is much interest in GSK3β as a potential therapeutic target in many types of cancer." (PMID 27087918, 2016). "While all these suggest that targeting GSK3β might be an important and effective means of controlling cancer progression, therapeutic options currently available are limited." (PMID 27602497, 2016). "It has been demonstrated that targeting GSK3β may represent a novel strategy for the treatment of chemoresistant cancers." (PMID 27792996, 2016). "Treatment of cancer cells with lithium carbonate significantly increased GSK-3β phosphorylation." (PMID 26857144, 2016). "Since activation of GSK3β destabilizes PD-L1, which inhibits T-cell immunity, we hypothesized that GSK3β may regulate cancer immunosuppression via PD-L1 destabilization." (PMID 27572267, 2016). "GSK3β knockdown promotes several kinds of cancer proliferation and metastasis by promoting β-catenin translocation into nucleus and upregulated oncogene snail expression to promote cancer cells metastasis." (PMID 26822534, 2016). "Glycogen synthase kinase-3β (GSK-3β) is a serine/threonine kinase involved in cancer development." (PMID 27050373, 2016). "Therefore the pharmacological inhibitors more quickly inhibit GSK-3β activity in cells and lead to a stronger biological effect on cancer cells than treatment with GSK-3β-specific siRNA." (PMID 27780915, 2016). "Despite this complexity, our studies provide a novel insight towards a pathway in which TZD can antagonize GSK3β expression and might be effective in targeting those cancers which rely on GSK3β activity for proliferation and survival." (PMID 27602497, 2016). "It has been reported that β-escin induces cancer cell death through the mitochondrial caspase dependent pathway, inhibition of NF-κB signalling and GSK3β/β-catenin pathway indicating that the mechanism of action may be cell type dependent." (PMID 27589691, 2016). "To determine whether GSK3β-mediated PD-L1 destabilization affects cancer cell immunosuppression, we compared the immunosuppression activity of PD-L1 WT and 3SA both in vitro and in vivo." (PMID 27572267, 2016). "Similarly, GSK3β inhibition was shown to ameliorate apoptosis resistance in other types of cancer as well." (PMID 27602497, 2016). "Aberrant activation of GSK-3β/β-catenin pathway leads to enhanced EMT in various cancer cells." (PMID 26683365, 2016). "To date, however, no studies have shown cellular neoplastic transformation via the activation of proto-oncoproteins, or demonstrated an increased incidence of cancer development or mortality following treatment with lithium, the classical GSK-3β inhibitor prescribed in clinical practice." (PMID 27780915, 2016).